CAT (catalase)
Diseases named in the same sentence as CAT in open-access papers (continued):
Sharing a sentence is not in itself a finding about the gene and the disease.
depression (continued). "Fifty-eight paediatric and adolescent patients with depressive disorder and 20 healthy controls were evaluated for oxidative stress markers (8-IsoP-U, LP, AOPP, NT, TEAC, SOD, GPx and CAT) and their correlations with the depression severity or the serum omega-6/omega-3 ratio." (PMID 34439504, 2021). "However, findings for the postpartum samples showed only a trend of association between the expressions of CAT, CD59, and RAPH1 blood markers and depression scores." (PMID 33479202, 2021). "We also found that CAT levels were positively associated with HAMD-17 scores at baseline in trBD depression and decreased after 6 weeks of ECT, which suggested that CAT levels could indicate the severity of trBD depression." (PMID 31967315, 2020). "More specific, the reduced levels of enzymatic and non-enzymatic antioxidants, including glutathione, zinc, uric acid, vitamins A, E, C, coenzyme Q10, glutathione peroxidase (GPx), superoxide dismutase (SOD), and catalase (CAT) were observed in the course of depression." (PMID 32545212, 2020). "However, our studies have showed that decrease in the activity of catalase is dependent on Geriatric Depression Scale in poststroke patients." (PMID 25838867, 2015). "On the other hand, other works detected lowered activity of catalase in depression." (PMID 26078821, 2015). "However, some studies have shown increased catalase activity during acute periods of depression." (PMID 37713054, 2024). "Additionally, catalase overexpression improves memory and reduces anxiety symptoms even in the absence of altered oxidative stress, and antidepressant treatment appears to increase levels of this antioxidant enzyme in patients with depression." (PMID 36901407, 2023). "It was hypothesized that oxidative stress acts as a primary crosslink between gastric cancer and depression and that depressive patients show decreased levels of antioxidants, including catalase and superoxide dismutase (SOD), as well as glutathione peroxidase (GPX)." (PMID 38068839, 2023). "Similarly, catalase activity increased in the nucleus accumbens of rat brains after administration of quetiapine, an atypical antipsychotic used also in the pharmacotherapy of depression." (PMID 32281745, 2020). "However, cases of reduced catalase activity were also described in depression." (PMID 32517269, 2020). "It is demonstrated that silymarin and silybin improve neurogenesis in the prefrontal cortex and hippocampus by modulating SOD and catalase (CAT) activities, alleviating symptoms of depression and anxiety." (PMID 39968181, 2025). "In depression, MDA levels increase in brain tissue, while the levels of the antioxidant enzymes GSH, CAT, and SOD are reduced." (PMID 40225229, 2025). "On the other hand, maqui berries improved health in post-stroke depression by increasing the level of GSH expression and increasing the activity of SOD and CAT." (PMID 36768580, 2023). "Spearman’s correlation results between the Polish PREM-C9 and CAT were as follows: rho = 0.44, p = 0.003539; HADS-Anxiety: rho = 0.370864, p = 0.015612; and HADS-Depression: rho = 0.387405, p = 0.011253." (PMID 37893819, 2023). "This was the first study to assess the intensity of depression symptoms and their relationship with TBARS, SOD, and CAT activity in master athletes." (PMID 36901407, 2023). "In the patients with depression before treatment, we observed positive correlations of HAM-D scale scores with serum CAT and urinary S-Nitrosothiols, as well as positive correlations of BDI scores with serum GSH and SOD." (PMID 38002663, 2023). "The NBP treatment group has higher levels of both SOD and catalase (CAT), and lower levels of both MDA and proinflammatory cytokine (IL-1β and IL-6) were found in major depressive disorder (MDD) rats, diabetic rats, EAM guinea pigs, and BMSCs." (PMID 35422893, 2022).
depression (continued). "Increased ROS induced by oxidative stress in the pathological mechanism of ME/CFS induces depression- or pain-like behaviors through decreased levels of anti-oxidative enzymes, such as SOD, catalase, and glutathione, and increased lipid peroxidation." (PMID 34638540, 2021). "Along this line, FLX has been shown to revert brain oxidative damage by reducing lipid peroxidation and increasing the activity of the antioxidant enzymes (i.e., CAT and SOD) in the hippocampus of an animal model of depression." (PMID 35002742, 2021). "Compared with these two groups, higher levels of SOD, CAT, and GSH-Px but lower levels of CRP, IL-6 and TNF-α were observed in the depression group." (PMID 32973539, 2020). "The product of lipid peroxidation, malondialdehyde (MDA) and activities of antioxidative enzymes such as catalase (CAT) and superoxide dismutase (SOD), along with reduced glutathione (GSH), also indicate the role of oxidative stress in depression." (PMID 32971941, 2020). "Decreased SOD, CAT, and GPx activities and elevated MDA levels have been identified in patient with recurrent depression." (PMID 29744362, 2018). "Similarly, in a depression model, EMPA increased GSH and CAT levels, reduced lipid peroxidation, and increased BDNF levels." (PMID 41011131, 2025). "Reduced antioxidant status in depression, characterized by significantly reduced levels of non-enzymatic antioxidant molecules, is usually associated with a decrease in GPX, CAT, and SOD activity in the blood." (PMID 39942624, 2025). "Increases in oxidative markers such as lipid peroxidase (LPO), TBARS, and MDA, along with decreases in antioxidant enzymatic systems (glutathione (GSH), catalase (CAT), superoxide dismutase (SOD), and glutathione peroxidase (GPX)), are observed in depressive disorder." (PMID 40943672, 2025). "Various studies on patients with major depression indicate that there is a considerable decrease in enzymes with great antioxidant power; this includes superoxide dismutase (SOD), glutathione peroxidase (GSH-Px), and catalase (CAT)." (PMID 39585071, 2024). "To verify whether music protects CUMS mice from depression-like behaviors by altering oxidative stress levels, we examined the expressions of NO, SOD, GSH, MDA, CAT, and GSH-Px in the mouse hippocampus, cortex, and serum." (PMID 37828015, 2023). "Increased activities have been detected in some studies, but on the other hand, several studies have published mixed or negative results for catalase activity in depression compared to healthy control groups." (PMID 36901407, 2023). "On the other hand, the CAT/TBARS ratio has a negative correlation with symptoms of depression [r = −0.3694 (p = 0.0344)]." (PMID 36901407, 2023). "In addition, maqui berries had an anti-depressive effect against post-stroke depression by upregulating expression levels of reduced glutathione (GSH) and enhancing the activities of SOD and catalase (CAT)." (PMID 36358502, 2022). "Additionally, RSV declines stress and depression mood in rats by improving GSH, SOD, and catalase content and decreasing MDA, lipid peroxidation, and corticosterone." (PMID 34621902, 2021). "Furthermore, overexpression of STC1 resulted in enhanced neural plasticity, reduced release of pro-inflammatory proteins, elevated SOD and CAT and diminished MDA level in the hippocampus of rats with depression-like behaviors." (PMID 34194345, 2021). "Moreover, there was a significant reduction in some important ROS scavengers including superoxide dismutases (SOD), catalase (CAT), and glutathione peroxidase (GSH-Px) in rodent models of depression." (PMID 35058758, 2021). "The SSRI fluoxetine (FLX) is able to revert the brain oxidative damage by reducing lipid peroxidation at hippocampal level, also increasing the activity of antioxidant enzymes, such as superoxide dismutase (SOD) and catalase (CAT), in different animal models of depression." (PMID 35002742, 2021).
depression (continued). "Similarly, previous studies found that chronic ozone inhalation induced depression‐like symptoms, including anxiety, and reduced cortical and hippocampal SOD and CAT activity." (PMID 32281745, 2020). "We demonstrate a positive correlation between the concentration of carbonyl groups and the Geriatric Depression Scale and a negative correlation between the degree of depression and the concentration of -SH groups or catalase activity." (PMID 25838867, 2015). "However, a meta-analysis of 8 studies from 2020 found higher CAT in BD patients compared to the healthy group, and CAT levels did not significantly differ in patients with mania, depression, or euthymia." (PMID 39324118, 2024). "Similarly, our study showed an increased activity in antioxidant defenses, mainly catalase, and a negative correlation between the intensity of depression symptoms and catalase activity in master athletes." (PMID 36901407, 2023). "Therefore, we aimed to analyze catalase, oxidative stress, and the intensity of depression symptoms in master athletes, their non-athlete peers, and a young control group." (PMID 36901407, 2023). "Moreover, in people with depression, there are disturbances in activity and a decrease in the expression of enzymatic antioxidants, such as superoxide dismutase (SOD), catalase (CAT), and enzymes related to glutathione metabolism: peroxidase, reductase, and S-transferase." (PMID 36768580, 2023). "It is also hypothesized that there is a negative correlation between catalase activity and the intensity of depression symptoms." (PMID 36901407, 2023). "We hypothesized that master athletes have higher catalase activity and lower intensity of depression symptoms when compared to their non-athlete peers and the youth control group." (PMID 36901407, 2023). "Moreover, the MI+ depression model also exhibited similar results to those of the IM group in terms of echocardiography (EF and FS), cardiac markers (CK-MB and LDH), antioxidants (SOD, GSH-Px, and CAT) and inflammatory factors (CRP, IL-6, and TNF-α)." (PMID 32973539, 2020). "During this oxidative process, increased lipid peroxidation and altered levels of antioxidant defenses, such as glutathione (GSH), CAT, and SOD enzymes, occur; therefore, strong antioxidants could be a promising approach to offering protection against anxiety and depression." (PMID 27822336, 2016). "Although there was a decrease in nitrite content and beta-adrenergic receptor binding in the patients with major depression as compared to that in the healthy controls, the activities of SOD, catalase, and GPX were not significantly altered in these patients." (PMID 24383611, 2014).
Parkinson disease (85 papers, 2010 to 2026). A progressive degenerative disorder of the central nervous system characterized by loss of dopamine producing neurons in the substantia nigra and the presence of Lewy bodies in the substantia nigra and locus coeruleus. "Oxidative stress is associated with neurodegeneration in Parkinson’s patients, with etiology attributed to a deficiency of natural anti-oxidants such as catalase, glutathione, and superoxide dismutase in the midbrain area." (PMID 40002364, 2025). "Catalase has also been implicated in the pathogenesis of neurodegenerative diseases such as Alzheimer’s and Parkinson’s disease." (PMID 39004753, 2024). "Catalase deficiency or malfunction is related to the pathogenesis of many age-associated degenerative diseases, such as DM, Alzheimer’s disease, Parkinson’s disease, and hypertension." (PMID 36671026, 2023). "In fact, catalase deficiency or malfunctioning was found to be associated with neurodegenerative disorders such as Alzheimer’s and Parkinson’s disease and neuron damage." (PMID 34572487, 2021). "A deficiency or malfunction of catalase has been recently related to the pathogenesis of age-associated degenerative diseases such as Parkinson’s disease and Alzheimer’s disease." (PMID 33371285, 2020). "As previously reported, Parkinson’s disease is associated with brain inflammation and, in the case of this disease, samples from brains showed reduced levels of catalase." (PMID 33371285, 2020). "The catalase activity reduction in the nerve terminals might be a sign of neuron damage; in fact, catalase deficiency or malfunctioning was found to be associated with neurodegenerative disorders, such as Alzheimer’s and Parkinson’s disease, and neuron damage." (PMID 35204705, 2022). "Reduced levels of catalase in neural cells have demonstrated a direct impact on the progression of neurodegenerative diseases, including Alzheimer’s (AD) and Parkinson’s (PD)." (PMID 40298834, 2025). "Catalase, a potent anti-oxidant, has shown the ability to protect primary cerebellar granule cells in Parkinson’s disease models." (PMID 40002364, 2025). "Oral administration of the AE increased activity of antioxidant enzymes (SOD, catalase, and glutathione peroxidase), and the concentration of dopamine in brain of Parkinson-type mice." (PMID 40649734, 2025). "Using macrophage-derived EVs, for instance, complete functional enzymes, like the antioxidant catalase, have been shown to be transported into the brain tissue in Parkinson’s disease models, even upon intranasal administration." (PMID 40430932, 2025). "This study presents Parkinson's Disease (PD)‐targeted carrier‐free nanocapsules (NCs) for the simultaneous delivery of dopamine and catalase to the PD brain, addressing both dopamine depletion and neuroinflammation." (PMID 39431293, 2024). "Increased levels of antioxidant enzymes such as NQO1, HO-1, catalase, etc., by the Nrf2 pathway provide a major defense against oxidative stress in Parkinson’s and stroke." (PMID 39062165, 2024). "Studies have reported decreased catalase activity in the brains of patients with Alzheimer’s and Parkinson’s disease, suggesting a role for oxidative stress in the development of these diseases." (PMID 39004753, 2024). "In the present study rotenone induced Parkinson effect also caused oxidative which ultimately reduced the activity of antioxidant enzymes like SOD and CAT." (PMID 39546440, 2024). "In another study, a potent antioxidant catalase was loaded into exosomes ex vivo and produced significant neuroprotective effects using in vitro and in vivo models of Parkinson’s disease." (PMID 37296618, 2023). "Catalase, a potent antioxidant, was delivered by macrophages-derived EVs by intranasal administration to treat Parkinson’s disease." (PMID 37717008, 2023). "Repeated freeze-thawing mediated catalase loading into vesicles provides a strategy of significant neuroprotection in an in vitro and in vivo model of Parkinson’s disease (PD)." (PMID 37362216, 2023).
Parkinson disease (continued). "Using these designer exosomes, the investigators delivered catalase mRNA across the blood–brain barrier, and inhibited neuroinflammation in the mouse model of Parkinson’s disease." (PMID 37717008, 2023). "In contrast, catalase administered by exosomes can reach the target neurons in a Parkinson's mouse model and accumulate in target cells." (PMID 36262830, 2022). "The system successfully made catalase cross the blood-brain barrier and reach the brain, thus improving the disease status of Parkinson’s disease." (PMID 36304147, 2022). "Recently, for successful delivery across the BBB, exosomes loaded with the antioxidant protein catalase showed an improved disease state in Parkinson’s disease patients." (PMID 34204903, 2021). "It is possible that degenerating neurons in these LTN1-hypomorphic mice harbor toxic CAT tail aggregates, as has been observed in a Drosophila model of Parkinson Disease." (PMID 31945107, 2020). "Catalase-loaded exosomes follow a sustained delivery with prolonged circulation time for treating Parkinson’s disease." (PMID 32957534, 2020). "Starting from this observation, these authors developed a formulation based on exosomes containing catalase and proposed it for Parkinson’s disease therapy." (PMID 33371285, 2020). "(2015) have developed an EV-based antioxidant and catalase delivery system for the treatment of Parkinson’s disease." (PMID 32264719, 2020). "(2015) reported earlier that macrophage-derived exosomes loaded with catalase can be considerably detected in brain of mouse with Parkinson’s disease following intranasal administration." (PMID 32264719, 2020). "In models of Parkinson's disease, EXOtic devices successfully ameliorated neurotoxicity and neuroinflammation by delivering catalase mRNA via EVs from implanted cells." (PMID 32724461, 2020). "Macrophage-derived EVs loaded with catalase provided increased neuroprotective effects in in vitro and in vivo models of Parkinson’s disease, compared to free catalase." (PMID 33224943, 2020). "It has been reported that samples from Parkinson’s disease brains have shown reduced levels of redox enzymes, catalase and superoxide dismutase." (PMID 33371285, 2020). "In a recent study, catalase loaded into macrophage-derived exosomes decreased oxidative stress and increased neuronal survival in vitro and in vivo in a mouse model of Parkinson’s disease." (PMID 31747944, 2019). "Repeated intra-nasal delivery of macrophage-derived EV loaded with catalase decreased microglial activation in the 6-hydroxydopamine (6-OHDA)-induced acute inflammation model of Parkinson’s disease." (PMID 31753024, 2019). "After intranasal administration of exosomes loaded with potent antioxidant, considerable amounts of catalase were detected in a Parkinson’s disease (PD) mouse brain model." (PMID 30861990, 2019). "Kabanov and coworkers demonstrated catalase/PEO-g-PEI micelles incorporated in a bone-marrow-derived macrophage system as a model for delivering catalase to Parkinson’s disease-affected regions in the brain." (PMID 31261765, 2019). "Since the present treatment of the 6-OHDA-based Parkinson’s model is entirely based on catalase delivery targeting ROS, we see only partial recovery, as ROS-independent cytotoxicities cannot be addressed by catalase treatment." (PMID 29610454, 2018). "Nanoformulated catalase was loaded into exosomes ex vivo which were tested in neuronal cells in vitro and Parkinson's disease mouse brain." (PMID 28912682, 2017). "Exosomal catalase showed efficient neuroprotective effects both in in vitro and in vivo models of Parkinson's disease." (PMID 28912682, 2017). "A formulation of catalase (exoCAT) obtained by drug-loading exosomes reached target neurons and accumulated in these cells in a Parkinson's mouse model." (PMID 28289371, 2017). "Brain of aged patients showed a reduced catalase functionality, similarly catalase activity was affected in a rat model of Parkinson’s disease." (PMID 25036594, 2014).